PWRN2 (Prader-Willi region non-protein coding RNA 2)
Synonyms: NCRNA00199
Gene: Long non-coding RNA gene on chromosome 15 (24,162,754 to 24,169,948, reverse strand). Ensembl gene ENSG00000260551.
Diseases named in the same sentence as PWRN2 in open-access papers:
PWRN2 is named in the same sentence as 4 diseases in open-access papers, as found by Europe PMC text mining. Sharing a sentence is not in itself a finding about the gene and the disease. The quoted sentences say what the papers report.
papillary thyroid carcinoma (1 paper, 2022). "PWRN2 sponges miR-325, to prevent miR-325 from targeting DDX5, thus promoting the progression of papillary thyroid carcinoma." (PMID 35992805, 2022).
polycystic ovary syndrome (1 paper, 2022). A disorder that manifests as multiple cysts on the ovaries. "In polycystic ovary syndrome (PCOS), a ceRNA network is constructed, most ceRNA axes are closely related to steroid biosynthesis and metabolic pathways, and PWRN2-mediated ceRNA may regulate oocyte nuclear maturation." (PMID 35935642, 2022).
PWRN2 also shares sentences with these, for which no sentence is quoted: Prader-Willi syndrome (1 paper); tauopathy (1).